SHISA8 (shisa family member 8)
Description:
May regulate trafficking and current kinetics of AMPA-type glutamate receptor (AMPAR) at synapses.
Synonyms: C22orf17; Orf26
Tractability: Antibody: UniProt predicts a signal peptide or a membrane-spanning region. PROTAC: ubiquitination databases record sites on it.
Gene: Protein-coding gene on chromosome 22 (41,909,543 to 41,915,074, reverse strand). Ensembl gene ENSG00000234965.
Subcellular location: Membrane
Gene Ontology:
Biological process: regulation of short-term neuronal synaptic plasticity
Cellular component: AMPA glutamate receptor complex; dendritic spine membrane; postsynaptic density; postsynaptic membrane; membrane
Genetic constraint (gnomAD): Loss-of-function variants: 22 observed, 12.51 expected, observed/expected ratio (o/e) 1.76, 90% interval 1.2 to 1.96. The synonymous counts are far from expectation, so gnomAD's model fits this gene poorly and the ratio says little. Missense variants: 535 observed, 392.94 expected, observed/expected ratio (o/e) 1.36, 90% interval 1.27 to 1.46. Synonymous variants: 300 observed, 208.96 expected, observed/expected ratio (o/e) 1.44, 90% interval 1.31 to 1.58.
Homologues: Orthologues: chimpanzee SHISA8 (99% identical), macaque SHISA8 (93% identical), pig SHISA8 (83% identical), mouse Shisa8 (81% identical), dog SHISA8 (80% identical), rat Shisa8 (71% identical), guinea pig SHISA8 (53% identical), tropical clawed frog shisa8 (31% identical), zebrafish shisa8b (31% identical), zebrafish shisa9b (28% identical), zebrafish shisa9a (26% identical). Paralogues in human: SHISA9 (29% identical), SHISA6 (27% identical), SHISA7 (25% identical).
Diseases named in the same sentence as SHISA8 in open-access papers:
SHISA8 is named in the same sentence as 1 disease in open-access papers, as found by Europe PMC text mining. Sharing a sentence is not in itself a finding about the gene and the disease. The quoted sentences say what the papers report.
tumor (2 papers, 2020 to 2024). "For CNS HGNET-BCOR detection, three probes for SHISA8, MNX1 and MMP15 showed diagnostic usefulness regardless of tumor location." (PMID 32650833, 2020).